CNTFR (ciliary neurotrophic factor receptor)
Description:
Functions either as a membrane-anchored non-signaling receptor via a GPI anchor or, after proteolytic release, as a soluble ligand-binding chaperone, and mediates signaling of CNTF-related cytokines, including ciliary neurotrophic factor (CNTF), cardiotrophin-like cytokine factor 1 (CLCF1), and the heterodimeric cytokine formed by CLCF1 and the cytokine receptor-like factor 1 (CRLF1). Involved namely in cell survival of motor neurons and regulation of oligodendrocyte progenitor proliferation. Functions within the ciliary neurotrophic factor receptor (CNTFR) complex as a membrane-anchored non-signaling receptor subunit associated with two other signaling receptor subunits IL6ST/gp130 and LIFR. Also, functions within the humanin receptor complex as a membrane-anchored non-signaling receptor subunit associated with IL6ST/GP130 and IL27RA/WSX1 that mediates the MT-RNR2/humanin signaling which induces neuroprotection. Alternatively functions as a soluble ligand-binding chaperone that binds ligand in the extracellular space, forming a cytokine complex which is delivered to the IL6ST/gp130 and LIFR signaling receptor subunits. Mechanistically, ligand binding to the CNTFR induces dimerization of the IL6ST/gp130 and LIFR (or IL27RA/WSX1 in the case of MT-RNR2/humanin), which activate JAK tyrosine kinases (JAK1 or JAK2 and to lesser extent TYK2) bound to their intracellular domains. These kinases subsequently phosphorylate IL6ST/gp130 and LIFR (or IL27RA/WSX1). The tyrosine phosphorylated signaling receptors serve in turn as docking sites for recruitment and activation of signal transducer and activators of transcription (STAT3 and to lesser extent STAT1).
Tractability: Antibody: its Gene Ontology location is reachable by antibodies, with high confidence; UniProt places it where antibodies can reach, with medium confidence; UniProt predicts a signal peptide or a membrane-spanning region. PROTAC: its protein half-life has been measured.
Gene: Protein-coding gene on chromosome 9 (34,551,423 to 34,593,478, reverse strand). Ensembl gene ENSG00000122756.
Subcellular location: Cell membrane; Secreted
Pathways (Reactome):
Immune System: IL-6-type cytokine receptor ligand interactions
Gene Ontology:
Molecular function: ciliary neurotrophic factor receptor activity; cytokine activity; cytokine binding; cytokine receptor activity; protein binding; protein carrier chaperone; signaling receptor binding; interleukin-11 binding; interleukin-11 receptor activity; signaling receptor activity
Biological process: ciliary neurotrophic factor-mediated signaling pathway; cytokine-mediated signaling pathway; negative regulation of neuron apoptotic process; negative regulation of oligodendrocyte progenitor proliferation; nervous system development; positive regulation of cell population proliferation; signal transduction; interleukin-11-mediated signaling pathway
Cellular component: apical plasma membrane; ciliary neurotrophic factor receptor complex; CNTFR-CLCF1 complex; external side of plasma membrane; extracellular region; humanin receptor complex; protein-containing complex; extrinsic component of membrane; plasma membrane; membrane
Genetic constraint (gnomAD): Loss-of-function variants: 12 observed, 35.52 expected, observed/expected ratio (o/e) 0.34, 90% interval 0.22 to 0.55. The upper end of that interval is the gene's LOEUF score, 0.55, which puts it in group 2 of 6, group 1 being the genes least tolerant of losing a copy. Missense variants: 414 observed, 475.05 expected, observed/expected ratio (o/e) 0.87, 90% interval 0.8 to 0.94. Synonymous variants: 202 observed, 201.56 expected, observed/expected ratio (o/e) 1, 90% interval 0.89 to 1.13.
Homologues: Orthologues: chimpanzee CNTFR (99% identical), rabbit CNTFR (98% identical), dog CNTFR (98% identical), pig CNTFR (96% identical), guinea pig CNTFR (95% identical), mouse Cntfr (95% identical), rat Cntfr (94% identical), macaque CNTFR (94% identical), tropical clawed frog cntfr (64% identical), zebrafish cntfr (48% identical). Paralogues in human: IL11RA (25% identical), CSF3R (21% identical), IL6R (21% identical), EBI3 (19% identical), IL12RB2 (17% identical), IL6ST (16% identical), CRLF1 (15% identical), OSMR (14% identical), LIFR (14% identical), IL27RA (13% identical), LEPR (12% identical), IL23R (11% identical), and 11 more.
Diseases named in the same sentence as CNTFR in open-access papers:
CNTFR is named in the same sentence as 28 diseases in open-access papers, as found by Europe PMC text mining. Sharing a sentence is not in itself a finding about the gene and the disease. The quoted sentences say what the papers report.
breast carcinoma (3 papers, 2020 to 2024). "In addition, the BC_gBRCA2 group showed overexpression of RIMS4 indicative of estrogen-positive cancers as well as CNTFR, which is shown to be deregulated in breast cancer, however, with unknown clinical impact." (PMID 33525353, 2021).
gastric cancer (2 papers, 2020 to 2022). A primary or metastatic malignant neoplasm involving the stomach. "Gene CNTFR has been implicated in rheumatoid arthritis, a chronic inflamatory disorder, and UBR4 in anorectal malformations and stomach cancer." (PMID 35105309, 2022).
ovarian carcinoma (2 papers, 2024). A malignant neoplasm originating from the surface ovarian epithelium. "Our results showed that CLCF1 or CNTFR knockdown did not affect DDP-induced cytotoxicity in ovarian cancer cells." (PMID 39256356, 2024).
acute myeloid leukemia (1 paper, 2020). Acute myeloid leukemia (AML) is a group of neoplasms arising from precursor cells committed to the myeloid cell-line differentiation. "miR-146a can induce the activation of JAK2-STAT3 pathway via down-regulating CNTFR, thereby affecting cell proliferation, migration, invasion and apoptosis in acute lymphatic leukemia and acute myeloid leukemia." (PMID 34079750, 2020).
Alzheimer disease (1 paper, 2023). A progressive, neurodegenerative disease characterized by loss of function and death of nerve cells in several areas of the brain leading to loss of cognitive function such as memory and language. "Extracellularly, following binding to the CNTFR/WSX-1/GP130 receptor complex, humanin can induce neuroprotection against mechanisms of Alzheimer’s disease pathology in a neuronal cell line via a STAT3 related mechanism." (PMID 37483601, 2023).
dementia (1 paper, 2025). Loss of intellectual abilities interfering with an individual's social and occupational functions. "Top proteins with high feature importance in the clinical impairment signature again highlighted ACHE and NPTXR as well as additional targets linked to neuroplasticity (EPHA4 and CNTFR) and immune activation (MSMP and KLK3), underscoring their potential for transdiagnostic dementia staging." (PMID 40665048, 2025).
glioma (1 paper, 2020). A benign or malignant brain and spinal cord tumor that arises from glial cells (astrocytes, oligodendrocytes, ependymal cells). "CNTFR-alpha has been associated with proliferation and poor prognosis and been proposed as a biomarker of low-grade gliomas." (PMID 32318098, 2020).
liver cancer (1 paper, 2024). An epithelial or non-epithelial malignant neoplasm that arises from the liver. "Cardiotrophin-like cytokine factor 1 (CLCF1) is an interleukin-6 (IL-6) family member secreted by cancer-associated fibroblasts (CAFs) that binds to ciliary neurotrophic factor receptor (CNTFR), promoting tumor growth in lung and liver cancer." (PMID 38562778, 2024).
melanoma (1 paper, 2022). A malignant, usually aggressive tumor composed of atypical, neoplastic melanocytes. "In this study, we presented the first evidence on CNTFR as a tumor progression-promoting gene and its prognostic value for melanoma." (PMID 36034849, 2022). "Unfortunately, the role of CNTFR in melanoma in modulating tumor growth and sensitivity to immunotherapy have obtained much less attention." (PMID 36034849, 2022). "After co-culturing CNTFR silenced melanoma cell lines (A375 and A875) with PMA-induced M0 macrophages for 48 h, the expression levels of macrophage polarization markers were evaluated." (PMID 36034849, 2022). "Taken together, the expression of CNTFR in melanoma cell lines proved a pivotal role in macrophage recruitment in TME." (PMID 36034849, 2022). "It was found that the CNTFR silenced in melanoma cell lines increased the mRNA levels of INOS in THP-1 derived macrophages, whereas inhibited ARG1 expression." (PMID 36034849, 2022). "As a consequence of the molecular biology experiments, we have found that inhibiting CNTFR activity exerted a reverse regulatory role in the proliferation and migration of melanoma cells, but facilitated the expression of immune checkpoints (PD-1, PD-L1, and CTLA4)." (PMID 36034849, 2022). "To further detect the regulatory role of CNTFR in melanoma cell lines, we examined whether the silencing of CNTFR played an indispensable role in the proliferation and migration of A375 and A875 cells." (PMID 36034849, 2022). "On the whole, the findings of pharmacology experiments further emphasized the pivotal function of si-CNTFR, as a novel supplement of chemotherapeutic drugs that could provide a valid therapeutic option for patients suffering from melanoma." (PMID 36034849, 2022). "Finally, in vitro molecular biology experiments were performed to assess the regulatory role of CNTFR in melanoma cell lines proliferation and migration, macrophage recruitment, and M2 polarization." (PMID 36034849, 2022). "Furthermore, to investigate the effect of chemotherapy drugs (ABT-263 and ABT-888) and si-CNTFR combined therapy on the proliferation of melanoma cell lines." (PMID 36034849, 2022). "Finally, CNTFR might function as oncogenes in melanoma cell lines and the silencing of CNTFR reduced macrophage recruitment and M2 polarization." (PMID 36034849, 2022).
mental disorder (1 paper, 2024). A disease that has its basis in the disruption of mental process. "A number of studies demonstrate that impaired CNTF signaling caused by mutations in the genes of the receptor complex CNTFR*gp130 (CNTFR and IL6ST genes, respectively) may contribute to mental disorders." (PMID 38646100, 2024).
neuroectodermal tumors (1 paper, 2023). "Remarkably, we found that, among different tumors, CNTFR showed the highest expression in SCLC and NB, which are two MYCN-related neuroectodermal tumors." (PMID 36765949, 2023).
osteoporosis (1 paper, 2021). A condition of reduced bone mass, with decreased cortical thickness and a decrease in the number and size of the trabeculae of cancellous bone (but normal chemical composition), resulting in increased fracture incidence. "Crlf1 is a member of the ciliary neurotrophic factor receptor pathway, and is involved in the anabolic therapy of osteoporosis through regulating osteoblast proliferation and bone formation." (PMID 33568122, 2021).
pancreatic cancers (1 paper, 2022). "Notably, the CNTFR was a promising therapeutic candidate for the treatment of a variety of tumors such as lung, colon, and pancreatic cancers and may portend specific biomarkers of increasing sensitivity." (PMID 36034849, 2022).
tumor (13 papers, 2020 to 2025). "For instance, CAFs-derived cardiotrophin-like cytokine factor 1 (CLCF1) engages ciliary neurotrophic factor receptor (CNTFR) on tumor cells, promoting the release of CXCL6 and TGF-β." (PMID 41445734, 2025). "CNTFR mRNA expression in MNA–NB cells (Kelly) was reduced after BGA002 administration, which also extended the relationship between MYCN and CNTFR in another MYCN-related tumor." (PMID 36765949, 2023). "Depleting these mediators or receptors on respective immune cells (ie, CCR2 and CNTFR) can reignite antitumor immunity and constrain tumor growth, rendering these factors attractive therapeutic targets." (PMID 36708970, 2023). "Using a murine model engrafting CAFs-HCC cells followed by tail-vein infusion of human neutrophils, they showed that CLCF1 or CNTFR depletion abrogated neutrophil recruitment and tumor proangiogenic growth triggered by CAFs." (PMID 36708970, 2023). "The interaction of CLCF1 with its receptor on HCC cells (CNTFR) contributes to N2 neutrophil infiltration and tumor propagation." (PMID 36708970, 2023). "In the tumor model BoC32, we observed in SR tumors an upregulation of IL-6 family members such as Ciliary Neurotrophic Factor Receptor (CNTFR) and Interleukin 6 receptor (IL6R), known to be able to signal via Janus kinase (JAK)/(STAT)." (PMID 34271981, 2021). "According to the biomarker classification, CNTFR-alpha presented the highest value, which means that it was active in all tumor samples analyzed and inactive in all normal samples." (PMID 32318098, 2020). "Moreover, in a panel of several different tumor types, CNTFR showed low mRNA expression in the majority of the tumors, while in NB (which is known for its connection with MNA and MYCN overexpression) and in SCLC it showed the highest expression." (PMID 36765949, 2023). "Finally, we also found that CNTFR specific inhibition can efficiently reduce cell viability in MNA-SCLC cells, confirming the importance of CNTFR in this tumor subtype." (PMID 36765949, 2023). "They found that the knockdown of CNTFR in mouse lung tumour cells decreases tumour growth." (PMID 35055176, 2022). "This also provides essential information that STIL, as an estrogen receptor signaling-related gene, in DLBCL, may regulate growth signals by targeting CNTFR and play a role in regulating tumor growth and development." (PMID 36531013, 2022). "The eight-gene-signature prognostic model (ANGPTL5, CD1B, CD1E, CNTFR, CTSG, EDN3, IL12B, and IL2)-based high- and low-risk groups were significantly related to overall survival (OS), tumor microenvironment (TME) immune cells, and clinical characteristics in LUAD." (PMID 34745015, 2021). "The CNTFR gene was reported as a new marker for NSCLC assessment and a potential therapeutic target, particularly for its correlation with tumor growth, differentiation modulation and pro-inflammatory cytokines stimulation." (PMID 36765949, 2023). "Overall, blockade of CLCF1/CNTFR signalling could be a novel therapeutic opportunity for LUAD and potentially for other tumour types in which CLCF1 is present in TME." (PMID 35055176, 2022).
CNTFR also shares sentences with these, for which no sentence is quoted: cancer (4 papers); lung carcinoma (3); Obesity (2); autoimmune disease (1); cervical cancer (1); colon cancer (1); lung adenocarcinoma (1); myeloid leukemia (1); neuroblastoma (1); non-small cell lung carcinoma (1); rheumatoid arthritis (1); stomach cancer (1); thyroid cancer (1); type 2 diabetes mellitus (1).